CD24 (CD24 molecule)
Diseases named in the same sentence as CD24 in open-access papers (continued):
Sharing a sentence is not in itself a finding about the gene and the disease.
breast cancer (continued). "Herein, we report that CD24 is under dynamic regulation in vivo and in vitro in five breast cancer cell lines." (PMID 19906290, 2009). "Our interest was in broadening the understanding of regulation of the CD24 gene and the invasive, mesenchymal CD44posCD24neg population in breast cancer cell lines." (PMID 19906290, 2009). "Several other studies have used putative CSC markers such as CD44+/CD24-/low to identify similar populations within breast cancer cell lines, but given that CD44 is a basal marker, this phenotype did not isolate the tumorigenic population." (PMID 19555472, 2009). "Data presented above suggests that CD24 expression is dynamically regulated in immortalized breast cancer cell lines." (PMID 19906290, 2009). "A relationship between CD24 and basal or luminal phenotype in breast cancer cell lines was reported by Fillmore and Kupperwasser." (PMID 19906290, 2009). "We demonstrate an association of the CD44+/CD24- phenotype to basal-like and BRCA1 hereditary breast cancer." (PMID 18559090, 2008). "All cell lines derived from another mammary tumor exhibited low levels of CD44+/CD24- cells, but they harbored 2% to 5.9% CD133+ cells, which were previously associated with cancer stem cells in other human and murine tumors." (PMID 18241344, 2008). "Contradictive to results by Al-Hajj and colleagues demonstrating CD44+/CD24- cells in all their breast cancer samples, we only detected cells with this phenotype in 31% of our tumors." (PMID 18559090, 2008). "Taken together, these data show that CD44+/CD24-/ESA+ cells in breast cancer lines exhibit increased resistance to chemotherapy, providing evidence for a mechanism of post-treatment recurrence." (PMID 18366788, 2008). "Based on this result, we selected MDA-MB-231 as negative control and MCF-7 as an experimental cell line for examining the effect of CD24 cross-linking on the growth of breast cancer cells." (PMID 18433506, 2008). "We found that CD24 cross-linking exhibited an inhibitory effect on breast cancer cell growth in the three-dimensional culture system." (PMID 18433506, 2008). "In breast cancer, CD24 mediates progression, metastasis, and rolling of tumor cells through interactions with P-selectin." (PMID 18433506, 2008). "A population of CD44+/CD24-/low cells has been demonstrated to have tumor-initiating properties in breast cancer." (PMID 18559090, 2008). "Since BrCSCs have been identified as CD44+CD24- subpopulation from breast cancer patient samples, much progress in research on this field has been achieved." (PMID 18477410, 2008). "Brca1-deficient mouse mammary tumors harbor heterogeneous cancer stem cell populations, and CD44+/CD24- cells represent a population that correlates with human breast cancer stem cells." (PMID 18241344, 2008). "Cell lines derived from a tumor with EMT features, 0_A1, lost expression of keratins, and contained a distinct subpopulation of breast cancer stem cells that express CD44+/CD24- markers." (PMID 18394172, 2008). "All cell lines derived from one tumor included increased numbers of CD44+/CD24- cells, which were previously identified as human breast cancer stem cells." (PMID 18241344, 2008). "All cell lines derived from A1 tumor (A1.1, A1.8, and A1.10) exhibited a higher (1.32% to 5%) fraction of CD44+/CD24- cells, which correlate with the phenotype of human breast cancer stem cells." (PMID 18241344, 2008). "Although expression of CD24 negatively correlated with stem cell characteristics in human breast cancer, the situation is more complex in mouse mammary tumors." (PMID 18241344, 2008). "In the present study, we have explored the dual expression of CD44 and CD24 in a sample of 240 stage II breast tumors with specific regard to breast cancer subtypes." (PMID 18559090, 2008). "We have explored the prevalence of cells with different CD44/CD24 phenotypes within breast cancer subtypes." (PMID 18559090, 2008).
breast cancer (continued). "We analyzed the presence of CD44 and CD24 antigens on human breast cancer tissues using double-staining immunohistochemistry." (PMID 18559090, 2008). "We did to study directly impact on cross-linking with CD24 (FL-80) antibody in MCF-7 human breast cancer cell line." (PMID 18433506, 2008). "The aim of this study was to further clarify the role of CD24 in breast cancer cell growth using a cross-linking approach." (PMID 18433506, 2008). "Brca1-deficient mouse mammary tumors harbor heterogeneous cancer stem cell populations, and CD44+/CD24- cells also identify human breast cancer stem cells." (PMID 18241344, 2008). "We correlated the presence of CD44+/CD24- cells to two gene signatures with prognostic value specific for either CD44+ or CD24+ breast cancer cells published by Shipitsin and colleagues." (PMID 18559090, 2008). "A recent study by Shipitsin and coworkers implicated that CD24+ and CD44+ cells within breast carcinomas represent defined cell populations with distinct genetic profiles." (PMID 18559090, 2008). "In this report we show the relationship between CD44+/CD24- phenotype of breast cancer cells and discrete steps of the metastatic cascade." (PMID 17062128, 2006). "In our earlier studies the cytoplasmic/membranous expression of CD24 (CD24c-m) was found to represent an unfavourable prognostic index of breast cancer." (PMID 16892043, 2006). "We show that a subgroup of breast cancer cell lines with a higher percentage of CD44+/CD24- cells express higher levels of proinvasive genes and invade matrigel in vitro." (PMID 17062128, 2006). "The study documented that cytoplasmic-membranous expression of CD24 represented an extremely strong unfavourable prognostic factor in breast cancer." (PMID 16892043, 2006). "CD44 and CD24 have been shown to regulate invasion and metastasis of breast cancer cells either positively or negatively." (PMID 17062128, 2006). "We investigated the importance of the stem/progenitor phenotype defined by CD44 positivity and CD24 negativity for breast cancer cells to invade and metastasize." (PMID 17062128, 2006). "A subpopulation (CD44+/CD24-) of breast cancer cells has been reported to have stem/progenitor cell properties." (PMID 17062128, 2006). "Breast cancer cells with CD44+/CD24- subpopulation express higher levels of proinvasive genes and have highly invasive properties." (PMID 17062128, 2006). "Recently, induction of CD24 expression in breast cancer cells was found to stimulate their proliferation and numerous invasive properties, like motility and aggressiveness." (PMID 16892043, 2006). "Present study aimed at determining prognostic and predictive value of immunohistochemical determination of ER, pS2, MT, and CD24 expression in sections originating from 104 patients with breast cancer." (PMID 16892043, 2006). "Notably, we established a clinical link between CD24 and M-CSF expression in breast cancer patients, demonstrating that CD24 expression negatively correlates with M-CSF expression in breast cancer patients." (PMID 40783744, 2025). "In summary, CD24 has been confirmed to be overexpressed in a variety of cancers, including head and neck cancer, breast cancer, lung cancer, colorectal cancer, pancreatic cancer, hepatocellular carcinoma, ovarian cancer, urothelial carcinoma, prostate cancer and hematological malignancies." (PMID 40486886, 2025). "Furthermore, high expression of CD24 is correlated with more lymph node metastases, more advanced pathological stage, and shorter survival in breast cancer." (PMID 40835598, 2025). "Therefore, we elected to separately survey CD24+ EVs as a complementary subpopulation due to previous reports of CD24+ EVs as a serum biomarker for breast cancer." (PMID 40405296, 2025). "Moreover, CD24 has been found to be expressed in approximately 85% of invasive breast carcinomas, providing a robustly expressed target for breast cancer-derived EVs." (PMID 40405296, 2025).
breast cancer (continued). "Consequently, breast cancer stem cells were evaluated using flow cytometry, revealing that the proportion of CD24-/CD44+ cells was significantly higher in alpelisib-resistant cells compared to parental cells, as well as protein levels of CD44 and c-Myc." (PMID 40303291, 2025). "CD24 was overexpressed in 34% of the tested breast cancer cases." (PMID 40943144, 2025). "Moreover, since the five proteins CD9, CD24, CD63, CD81, and MMP9 are universal and present in exosomes secreted by both primary endotheliocytes and breast carcinoma cells, they cannot be part of the diagnostic panels being developed." (PMID 40310419, 2025). "Histopathological analysis of mice tumor sections revealed a higher accumulation of necrotic debris correlating with the higher tumorigenic potential of the CD24−/CD44+‐breast CSCs as compared with CD24+‐breast cancer cells xenotransplanted groups, which was quantified using Image J software." (PMID 38522013, 2024). "Employing algorithms, a regulatory interaction between miR-98 and the CD24 gene in breast cancer was identified, implying that miR-98 may play a functional role via CD24 targeting." (PMID 38872210, 2024). "Additionally, recent studies have identified a highly potent small‐molecule antagonist of exportin‐1, which selectively eliminates CD44+CD24− enriched breast cancer stem‐like cells." (PMID 38982317, 2024). "The migratory potential of the sorted CD24+‐breast cancer cells and CD24−/CD44+‐breast CSC populations in the presence of combinatorial treatment of Doxorubicin low dose (0.01 μM) and compound 1e (5 μM) was observed to be significantly reduced as compared to the positive control group (10% FBS)." (PMID 38522013, 2024). "Indeed, a subpopulation with CD44+ and CD24−/lower phenotype showed increased metastasis to bone in a mouse model of human breast cancer stem-like cells." (PMID 38392969, 2024). "Our study found that M funiformis can have an effect on breast cancer through CD38 on IgD+ CD24‐." (PMID 39654239, 2024). "We found that M funiformis had an effect on breast cancer through CD38 on IgD+ CD24‐." (PMID 39654239, 2024). "In breast cancer, CD24-/low/CD44+ and ALDH+ phenotypes are termed to be cancer stem cells." (PMID 39124569, 2024). "Several reports suggest that the development of resistance to doxorubicin involves cancer cells that acquire multidrug-resistant phenotypes, populations (CD44+/CD24 −/low) of breast cancer stem cells (CSCs), and initiation of the epithelial-mesenchymal transition (EMT)." (PMID 39180549, 2024). "Similarly, a significant increase in the colocalization of GFP and p‐EGFR (activated EGFR) was observed in the CD24−/CD44+‐breast CSC as compared with the CD24+‐breast cancer cell xenotransplanted groups." (PMID 38522013, 2024). "Siglec-10 binds CD24 on breast cancer cells and prevents macrophage-mediated phagocytosis, indicating that Siglec-10 may also suppress macrophage functioning." (PMID 38594506, 2024). "Research on the function of the CD24/Siglec-10 axis in controlling macrophage-triggered phagocytosis using human breast cancer MCF-7 cells has demonstrated that in an in vitro co-culture system, macrophages preferentially phagocytotize CD24-/-MCF-7 cells over wild-type MCF-7 cells." (PMID 38279998, 2024). "Furthermore, p27CK-DD expression in MCF12A causes a shift from predominantly CD44low/CD24+ to a greater population expressing stem cell surface markers, CD44+CD24low/-, a hall mark of breast cancer initiating cells or CSCs2." (PMID 38886396, 2024). "Using DISVT and our machine learning-assisted image analysis platform, we determined the fractions of EpCAM-positive EVs and CD24-positive EVs over captured plasma EVs with CD81 marker in the blood plasma of pilot HER2-positive breast cancer patients and compared to those from healthy donors." (PMID 39513819, 2024).
breast cancer (continued). "Epithelial circulating tumor cells (CTCs) were shown to be significantly correlated with ER expression (p = 0.036) and TNM stage (p = 0.018) in a recent study on the expression of CD24 in peripheral blood CTCs and the utility of CTCs in predicting the prognosis of breast cancer patients." (PMID 38279998, 2024). "Additionally, SDF-1 secretion by breast CAFs contributes to the proliferation of breast cancer stem cells (CD44+CD24-) and the induction of drug resistance." (PMID 38533507, 2024). "However, an increasing number of studies have observed cytoplasmic accumulation of CD24 in invasive and metastatic cancers, such as ovarian cancer, colorectal cancer, and breast cancer." (PMID 39791710, 2024). "Besides, it has been shown in breast cancer that β-catenin can inhibit tumor immune escape by down-regulating the expression of CD24." (PMID 37919766, 2023). "The role of CD24 in breast cancer is gaining increasing attention." (PMID 36882451, 2023). "Moreover, aldehyde dehydrogenase (ALDH) activity is recognized as a biomarker of breast cancer stem cells with a CD44+/CD24− phenotype." (PMID 36768815, 2023). "Moreover, it is possible that estrogen-mediated downregulation of CD24 expression is responsible for the high failure rate of selective estrogen receptor modulators in breast cancer treatment." (PMID 37907864, 2023). "Therefore, in murine breast cancer cells, a higher proportion of CD24 + /CD49f + subpopulation indicates stronger stemness, while a lower proportion of CD24 + /CD49f + subpopulation suggests weaker stemness." (PMID 38031089, 2023). "The synergistic effect of H2O2 self-supplying CDT and CBIT demonstrated by the dAbPD−L1/CD24-mPDA@CuO2 NRs in the acidic tumor microenvironment presents a promising drug-free synergistic therapy approach for breast cancer, particularly for the treatment of triple-negative breast cancer (TNBC)." (PMID 37875918, 2023). "Furthermore, a breast cancer stem cell subpopulation strongly associated with poor prognosis has been identified, which has been defined as CD79A+CD24-PANCK+-BCSCs subpopulation." (PMID 38066053, 2023). "Similarly, in human-derived breast cancer cells, a higher proportion of CD24-/CD44 + subpopulation indicates stronger stemness, while a lower proportion of CD24-/CD44 + subpopulation suggests weaker stemness." (PMID 38031089, 2023). "For example, it has been proven that quercetin suppressed the activation of PI3K and AKT, which increased the ratio of BAX/Bcl-2 to induce apoptosis of breast cancer cells, as well as significantly inhibiting the growth and metastasis of CD44+/CD24 breast cancer stem cells in vivo." (PMID 36900408, 2023). "Moreover, individual CSCs in SCC (CD44+CD34+ITGA6+), lung cancer (ASCL1+/CGRP+ neuroendocrine cell) and breast cancer (CD44+CD24-, GSE124887) show concurrent activation of stemness genes, nuclear factors and mitochondrial components." (PMID 37463926, 2023). "For example, exosomes isolated from breast cancer patient serum have been shown to express CD24, indicating exosomal CD24 could serve as a potential marker for breast cancer." (PMID 37190185, 2023). "Indeed, the CD44+/CD24-/low CSC phenotype is associated with the expression oh HIF-1α and poor survival of patients with breast cancer." (PMID 37064130, 2023). "In addition, CD24 was also revealed to be involved in the regulation of stemness and the epithelial to mesenchymal transition in breast cancer cells." (PMID 37919766, 2023). "Although CD44+/CD24- is considered a marker of BC stem cells, CD24 has been historically identified as a marker of cell signaling in tumors and recently has been reported as an anti-phagocytic surface protein on breast cancer cells." (PMID 37298091, 2023). "In breast cancer, the effects of CD24 on prognosis in terms of OS and DFS are controversial." (PMID 35037689, 2022). "The overexpression of PD-L1 seems to downregulate surface CD24 in breast cancer cells." (PMID 36013184, 2022).
breast cancer (continued). "In breast cancer, BCSCs were initially identified as the CD24−/CD44+ phenotype." (PMID 36230903, 2022). "In addition, the downregulation of FoxO3 leads to changes in the levels of CD44/CD24, which are breast cancer stem cell markers." (PMID 36142156, 2022). "Interestingly, four of those proteins (CD24, CD29, CD44 and CD146) have previously been associated with breast cancer." (PMID 35012489, 2022). "However, an article in 2003 demonstrated that CD44 and CD24 are viable cell surface markers for identifying breast cancer stem cells by in vivo xenograft formation of serially diluted xenograft tumor cells derived from multiple passaging in mice." (PMID 35883497, 2022). "In contrast to data gathered in breast cancer cells, the cell cycle profiles, proliferation rates, and the adhesion abilities were not different between CD24‐deficient and parental cells, but the migratory capacity trended to be increased." (PMID 34293822, 2022). "Much previous evidence supports the role of HER2 in RT resistance, and HER2+/CD44+/CD24−/low cells, Fak activation in vitro and in vivo, and STAT3-survivin signaling may be associated with RT resistance in HER2+ breast cancer patients." (PMID 36686782, 2022). "Hierarchical tumor organization was also shown in solid cancers, as for instance only CD44+/CD24-/low tumorigenic breast cancer cells were able to form tumors that contained additional CD44+/CD24-/low cells, as well as phenotypically different non-tumorigenic cells." (PMID 35328833, 2022). "Notably, current literature has suggested the critical role of RUNX2 for malignant progression of breast cancer by modulating the CD44 +/CD24- breast cancer stem cells." (PMID 36483054, 2022). "One study showed that TWIST1 binds to the promoter of CD24 and transcriptionally regulates CD24 expression, resulting in stem cell traits such as self-renewal and the ability to form mammospheres in breast cancer, suggesting that EMT-TFs are mainly involved in the BCSC phenotype." (PMID 35743249, 2022). "CD24 could thus be a prognostic biomarker and therapeutic target in breast cancer, but more in vitro and in vivo studies are needed to clarify its potential." (PMID 35037689, 2022). "Accordingly, CD24 blockade using a monoclonal antibody (mAb) induced macrophage-mediated phagocytosis of breast, ovarian, and pancreas cell lines in vitro and inhibited tumor growth of xenografted breast cancer cell line MCF-7 in an NSG mouse model." (PMID 35625912, 2022). "Cisplatin, which increased CD24 expression, is suggested to induce stem-to-progenitor differentiation in tpMDA and tsMDA, and this cisplatin-triggered cell differentiation was previously reported in breast cancer." (PMID 33919109, 2021). "However, the expression levels of CD24 and E-cadherin in breast cancer tissues were lower than those in adjacent tissues (P<0.05)." (PMID 34932597, 2021). "CD24 is a widely accepted cell surface marker for breast cancer stem cells." (PMID 34187256, 2021). "Mammospheres or breast cancer cells in hypoxia have higher expression of the KLF4, NANOG, OCT4, and SOX2 genes and CD44 and CD24, which encode pluripotency factors that are required for the maintenance of cancer stem cells, embryonic stem cells, and induced pluripotent stem cells." (PMID 34830821, 2021). "Similarly, the transient expression of Twist in several breast cancer cell lines induces transformation to a stem cell phenotype and transcriptionally regulates CD24 expression in bCSCs." (PMID 33802575, 2021). "Therefore, we aimed to investigate the role of N-glycosylation in the trafficking and subcellular localization of CD24 in luminal and basal B type of breast cancer cell lines." (PMID 34360932, 2021). "In addition, CD44 is regarded as a stemness marker of breast cancer stem cells (BCSCs) (CD44+/CD24−/low) in TNBCs." (PMID 33801148, 2021).